TIGIT (T cell immunoreceptor with Ig and ITIM domains)
Diseases named in the same sentence as TIGIT in open-access papers (continued):
Sharing a sentence is not in itself a finding about the gene and the disease.
tumor (continued). "In vitro, antibody blockade of PVR or PVRL2 on HCC cell lines or TIGIT blockade on immune cells increased immune cell-mediated lysis of tumor cell." (PMID 37383234, 2023). "Preclinical studies have demonstrated the potential benefits of co-inhibition of TIGIT and PD-1/PD-L1 in enhancing anti-tumor immunity and improving treatment outcomes in several cancer types." (PMID 37291608, 2023). "In this mechanism, Fap2 creates a bacterium-dependent, tumor immune evasion inhibiting T-cell activities via TiGIT." (PMID 37764202, 2023). "There is substantial evidence demonstrated in vivo and in vitro that the TIGIT pathway plays a role in T-cell-mediated and natural killer cell-mediated tumor recognition." (PMID 38203670, 2023). "Here, TIGIT blockades reduced tumor growth, promoting the infiltration of primary tumors by cytotoxic lymphocytes." (PMID 37444427, 2023). "Targeting some of these immune checkpoints as VISTA, LAG-3, Tim-3, and TIGIT led to additive effects and reactivation of tumor-specific T cells and clinical trials are still ongoing (NCT04475523, NCT02812875, (NCT0348936962–66." (PMID 37620318, 2023). "We also measured the protein expression of GITR and TIGIT in these baseline tumor tissues (T0 resections) using multiplexed immunofluorescence (mIF) staining." (PMID 38008725, 2023). "All these studies suggest that the increased expression of TIGIT in the TME leads to immune escape of tumor cells, thereby affecting the development and progression of tumors and the prognosis of patients." (PMID 37670328, 2023). "Immunoblot analysis showed that tumor cells infected with OAd-SIRPα-Fc, OAd-Siglec10-Fc or OAd-TIGIT-Fc efficiently secreted the corresponding fusion protein as a dimer into the supernatant in vitro." (PMID 38016957, 2023). "An alternative possibility is that TIGIT is a biomarker of a potent cytotoxic effector population similar to a recent study that showed NKG2A+ Vδ2 T cells possess enhanced anti-tumor capabilities." (PMID 37063856, 2023). "Taken together, these results identified the functional link between TIGIT/CD155 signaling and DCs in combination therapy and demonstrated that the combination of RT and anti-TIGIT therapy can enhance host anti-tumor immune responses." (PMID 35794399, 2023). "As a co-stimulatory receptor that mediates T cell adhesion and execution of cytotoxicity, CD226 competes with immune checkpoints like TIGIT for the same ligands expressed by cancer cells to execute the anti-tumor effects." (PMID 37398674, 2023). "Here, high numbers of TIGIT-expressing tumor infiltrating lymphocytes have been correlated with a poor survival rate." (PMID 36874131, 2023). "Blockade of immune checkpoint receptors such as PD1 or TIGIT with mAb was shown to restore NK cell effector functions against tumor cells." (PMID 36355079, 2023). "In accordance with this evidence, we observed that PD-1, TIM-3, and TIGIT in TILs were increased in FN-positive tumor tissues compared to those FN-negative tumors." (PMID 36960042, 2023). "Studies in murine models have demonstrated that TIGIT inhibits NK cells and promotes exhaustion, with its effects on tumor control also being dependent on NK cells." (PMID 37345049, 2023). "Using gene signatures of TCR signaling or T cell activation, we examined tumor-specific responses to TIGIT inhibition." (PMID 38008725, 2023). "In contrast to DNAM-1, TIGIT is weakly expressed by naive T cells; in cancer, it is co-expressed with PD-1 on tumour antigen-specific CD8+ T cells and CD8+ tumour-infiltrating lymphocytes (TILs) in humans." (PMID 37325585, 2023). "The CD155/TIGIT axis, for instance, plays a role in tumour immune evasion, similar to the PD-1/PD-L1 axis." (PMID 37803304, 2023). "Tregs expressed higher levels of inhibitory markers, such as HAVCR2/TIM3 and TIGIT in PT and tumour‐invaded TDLN." (PMID 37491740, 2023).
tumor (continued). "The anti-tumor immune response can be suppressed by TIGIT, which is an inhibitory molecule on CD8+ effector memory T cells, and inhibitors of TIGIT combined with anti-PD1 are promising to reduce PD1 inhibitor resistance." (PMID 36998605, 2023). "CD226 was a receptor molecule that competing with TIGIT for the same ligands, and has been shown to enhance the cytotoxic and anti-tumor responses of mouse NK cells." (PMID 37426809, 2023). "In peripheral blood, NKp46, NKG2D, and TIGIT expression were significantly upregulated in tumor-bearing mice, while high doses of aconite treatment downregulated the expression of all three receptors." (PMID 36756040, 2023). "The authors report an in-depth investigation of the PDAC tumor microenvironment that highlights PD-1 and TIGIT, or their corresponding ligands, as potential targets for combinatorial therapy to treat this devastating disease." (PMID 36689623, 2023). "At the same time, we also observed the changes of immune cell mediated killing effect of tumour cells by blocking TIGIT, and the results showed that the killing ability of the experimental group was significantly enhanced compared with the control group." (PMID 37383234, 2023). "A number of preclinical trials have shown that anti-TIGIT antibody and anti-PD-1/PD-L1 antibody function synergistically to provide anti-tumor effects and enhance the anti-tumor responses." (PMID 37063927, 2023). "Although the upregulation of TIGIT can exert immunosuppressive features in tumor immunity, literature revealed TIGIT+ CD8+ subsets with cytotoxic properties." (PMID 36776340, 2023). "To characterize the precise effects of OAds, we evaluated antitumor activity in three tumor models established with immunocompetent mice treated with an intratumoral injection of OAd-null, OAd-SIRPα-Fc, OAd-Siglec10-Fc, or OAd-TIGIT-Fc." (PMID 38016957, 2023). "CD226 can compete with the inhibitory receptors CD96 and T cell immunoreceptor with Ig and ITIM domain (TIGIT) expressed on T cells for binding to CD155 overexpressed in tumor cells to exert anti-tumor effect." (PMID 37312116, 2023). "Blocking TIGIT significantly promoted the release of cytokines, thereby enhancing the tumor-killing effects of the anti-MLSN-CAR-T cells." (PMID 37670328, 2023). "Our study demonstrated TIGIT blockade can synergistically enhance anti-tumor T cell responses to RT via CD8 + T cells (dependent on CD103 + DCs), suggesting the clinical potential of targeting the TIGIT pathway and expanding CD103 + DCs in RT." (PMID 35794399, 2023). "As NK and T lymphocytes enter the TME, they express TIGIT on their surface that interacts with the CD155 on tumor cells." (PMID 37345111, 2023). "In summary, these results indicated that anti-α-TIGIT enhanced the sustained killing effect of anti-MSLN CAR-T cells on tumor cells." (PMID 37359558, 2023). "The major immune checkpoints include PDCD-1, CD274 (also known as PD-L1), CTLA-4, HAVCR2 (also called TIM-3), LAG-3 and TIGIT which are responsible for tumor immune escape." (PMID 37810780, 2023). "Together, the additional treatment of tumor-bearing mice with either anti-TIGIT or anti-PD-L1 augmented the antitumor effects of the anti-GD2 immunotherapy with DB, with superior effects in the “DB + anti-PD-L1” experimental group." (PMID 37444427, 2023). "Taken together, these data demonstrate that the armed OAd-SIRPα-Fc, OAd-Siglec10-Fc and OAd-TIGIT-Fc can selectively lyse tumor cells and secrete high levels of functional fusion proteins." (PMID 38016957, 2023). "Treatment with a combination of RT and anti-TIGIT therapy effectively controlled tumor growth in the MC38 tumor model." (PMID 35794399, 2023). "Expression of CD163 and TIGIT was significantly higher in patients with a more aggressive and invasive tumor subtype." (PMID 37876933, 2023). "Here, we review the most recent literature on the reciprocal interaction of TIGIT and T cell metabolism and specifically how TIGIT affects anti-tumor immunity." (PMID 36874131, 2023).
tumor (continued). "Co-inhibitory receptor molecule TIGIT is a promising therapeutic target for tumor immunotherapy, with multiple clinical trials and preclinical trials underway." (PMID 37441080, 2023). "In mouse pre-clinical models and cancer patients, TIGIT expression on tumor-infiltrating CD8+ T cells often correlates with increased expression of other inhibitory receptors such as PD-1, LAG-3, TIM-3, and with decreased expression of DNAM-1." (PMID 37569880, 2023). "Overall, these results indicated that the proinflammatory effects modulated by TIGIT in various cell types in the TME translated into initial favorable transcriptional responses at 24 h in tumor epithelial cells." (PMID 38008725, 2023). "The present study demonstrated that freshly activated and/or expanded NK cells appear to have higher TIGIT expression, which also correlates to a more activated phenotype and enhanced anti-tumor function." (PMID 37345049, 2023). "It is therefore crucial to further investigate the potential direct and indirect effects of TIGIT on the metabolism of T cells and other immune cells in the context of anti-tumor immunity." (PMID 36874131, 2023). "Our results indicate that RT plus anti-TIGIT therapy improves tumor control by enhancing CD8 + T cell function in the TME and by enhancing systemic activation of tumor-specific T cells in distant tumors." (PMID 35794399, 2023). "In summary, our study demonstrated that blocking TIGIT effectively enhances the anti-tumor effect of CAR-T cells, thereby suggesting a promising strategy for the treatment of solid tumors by combining CAR-T cells with immune checkpoint blockages." (PMID 37359558, 2023). "Although TIGIT was expressed by a higher frequency of trNK cells in the tumor center compared to peritumoral and distal tissue, expression remained considerably lower than that of CD8+ TRM cells at all locations." (PMID 37448786, 2023). "This suggests that Flt3L, RT, and anti-TIGIT triple therapy can promote the induction of tumor-specific CD8 + T cell immunity." (PMID 35794399, 2023). "Since LAG3, PDCD1 and TIGIT have long been identified as key immune checkpoints in ccRCC, their blockade has demonstrated satisfactory anti-tumor efficacy in preclinical and clinical studies." (PMID 37679715, 2023). "During tumor progression, TIGIT is the main checkpoint responsible for functional exhaustion in NK cells." (PMID 37760586, 2023). "TIGIT also binds PVRL4 (Nectin-4), a TIGIT-specific ligand almost exclusively expressed on tumor cells." (PMID 37345049, 2023). "TIGIT inhibition not only enhances CD8 T-cell cytotoxicity but also boosts NK cell anti-tumor responses." (PMID 37291608, 2023). "TIGIT blockade also restored most of the ability of PM21-NK cells to degranulate upon PVR+ cell restimulation post-tumor-co-culture." (PMID 37345049, 2023). "TIGIT blockade upregulated multiple gene sets related to NK cell anti-tumor responses, including inflammatory response-related genes, TNFα signaling via NFкB, and IFNγ response-related gene sets." (PMID 37345049, 2023). "We identified that the TIGIT–PVR/PVRL2 axis provides a prominent coinhibitory signal in tumour-infiltrating immune cells and APCs." (PMID 37383234, 2023). "This review provides an overview of the mechanisms of TIGIT and PD-1/PD-L1 co-inhibition in anti-tumor treatment, summarizes the latest clinical trials investigating this combination therapy, and discusses its prospects." (PMID 37291608, 2023). "CD155 expressed on the surface of tumor cells can bind to TIGIT and negatively regulate NK cell function." (PMID 37511510, 2023). "We also found CD155 on both populations of MDCSs in tumor tissues and, importantly, we detected a clear TIGIT expression on these immune-suppressive cells, further emphasizing the rationale for blocking this pathway against NB." (PMID 37444427, 2023).
tumor (continued). "Blockade of TIGIT and other immune checkpoint targets as cancer immunotherapeutic strategies has been reported to be very promising in different pre-clinical mouse tumor models." (PMID 36829496, 2023). "Together, these heterogeneous distributions of immune variables associated with TIGIT and CD155 in tumor tissues highlight the spatial immune complexity in PDAC." (PMID 37649613, 2023). "Treatment with a combination of RT + anti-TIGIT also effectively controlled tumor growth in this model." (PMID 35794399, 2023). "Our study demonstrated that blocking TIGIT significantly promoted cytokine release to augment the tumor-killing effect of MT CAR-T cells." (PMID 37359558, 2023). "The overall abundance of CD226 + TIGIT+ co-expressing cells was low (<8% mean frequency) for each T cell subset within the tumour." (PMID 37596248, 2023). "The paradigm of anti-TIGIT and anti-PD-1/PD-L1 synergism exerting better tumour control and overall survival was taken forward in a large phase II trial; CITYSCAPE which reported in early 2022." (PMID 37325585, 2023). "When CD155 on the tumor surface binds to TIGIT on the surface of NK and T cells, it leads to immune escape of tumor cells and the anti-tumor effect is inhibited." (PMID 37359558, 2023). "The main inhibitory receptor that restricts DNAM-1 responses in the tumor microenvironment is TIGIT." (PMID 37760586, 2023). "Lack of TIGIT expression in NK cells in vivo retarded tumor growth, and blockade of TIGIT action via mAb reversed antitumor NK cell exhaustion in multiple tumor models, resulting in increased overall host survival." (PMID 37670328, 2023). "TIGIT is mainly expressed on tumor-infiltrating cytotoxic T cells, NK cells, etc., contributing to local suppression of immune surveillance via interacting with CD155." (PMID 37064147, 2023). "When CD155 is highly expressed on tumor cells, it binds TIGIT and promotes direct and indirect downregulation of T-cell response." (PMID 37109579, 2023). "In the bone marrow and peripheral blood of MM patients, based on the long-term impact of the tumor environment, NK cells showed immune exhaustion, characterized by upregulation of TIGIT and its multiple ligands." (PMID 37239949, 2023). "CD8+ Tex cells (TIM-3+TIGIT+) were clonally expanded and express markers of tumor-specificity (CD39+), and the majority of expanded clones were derived from novel clonotypes." (PMID 37881432, 2023). "An anti-human TIGIT IgG 4-type monoclonal antibody, MG1131, significantly enhanced the anti-tumor activity of NK cells by competitively binding TIGIT." (PMID 37239949, 2023). "In contrast, both combinations of DB, with either anti-TIGIT or anti-PD-L1 Ab, strongly inhibited tumor growth." (PMID 37444427, 2023). "PM21-NK cells were exposed to tumor spheroid for 7 days in the presence of anti-TIGIT or isotype control antibodies." (PMID 37345049, 2023). "Depletion of TIGIT+ populations including Tregs has been reported in tumor samples obtained from patients treated with Fc-optimized TIGIT antibodies and was considered important for the therapeutic effects of the antibodies." (PMID 37345049, 2023). "Dysfunctional anti-tumor T-cell responses have been linked to the elevated and sustained expression of numerous ICs (PD-1, CTLA-4, TIM-3, TIGIT, or LAG-3) in a variety of malignancies." (PMID 38130714, 2023). "Additional anti-TIGIT or anti-PD-L1 treatments effectively inhibited tumor growth and improved survival of the mice treated with DB." (PMID 37444427, 2023). "As discussed, TIGIT expression has been observed, among others, with PD-L1 in the tumor core, hinting at some kind of link between these two proteins." (PMID 36874131, 2023). "The results showed that the anti-α-TIGIT scFv-expressing group had a better tumor-killing effect compared to the antibody and IgG groups in Hela, HelaCD155 and Skov3 cells." (PMID 37359558, 2023).
tumor (continued). "Results revealed that TIGIT protein expression in IHC was negligible in the normal control group, while it was highly expressed in the tumor-bearing group and downregulated in the 125I radiation group." (PMID 37124530, 2023). "The results showed that the expression of TIGIT in the tumor control group was significantly increased compared with that in the normal control group and decreased in the 125I seed radiation group." (PMID 37124530, 2023). "Accumulating studies have demonstrated that elevated TIGIT expression in tumor microenvironment correlates with better therapeutic response to TIGIT-based immunotherapy in pre-clinical studies." (PMID 37129788, 2023). "In conclusion, we show that specific characteristics of the Fc backbone of the anti-TIGIT antibody are critical for antitumor activity preclinically across several syngeneic murine tumor models." (PMID 38022590, 2023). "When TIGIT inhibition was combined with anti-PD-1 inhibition in vitro, it was found to enhance tumor antigen specific CD8+ T cell expansion and activity, as compared with anti-PD-1 inhibition alone." (PMID 36674809, 2023). "This BsAb can enhance the role of immune surveillance by recognizing and killing tumor cells and blocking the potential synergistic effects of PD-1 and TIGIT to enhance antitumor effects." (PMID 37670328, 2023). "Among them, TIGIT has recently gained significant attention, since its targeting results in improved anti-tumor immune responses." (PMID 37760586, 2023). "In sharp contrast, blocking TIGIT and PD-1/PD-L1 gave highly synergistic results, including absolute tumor rejection with enhanced survival, and enhanced activation, memory, and antitumor functions of CD8 T cells." (PMID 36829496, 2023). "Our results suggested that OAd-SIRPα-Fc and OAd-Siglec10-Fc both showed outstanding efficacy in tumor suppression of macrophage-dominated tumors, while OAd-TIGIT-Fc showed the best antitumor immunity in CD8+ T-cell-dominated tumors." (PMID 38016957, 2023). "TIGIT is a co-inhibitory receptor highly expressed in tumor-infiltrating lymphocytes, which is a new immune checkpoint after PD-1/PD-L1." (PMID 38129374, 2023). "Surprisingly, besides ligand expression, we also observed on tumor-infiltrating MDCSs the expression of the receptor TIGIT, indicating an additional mechanism of action of this inhibitory pathway in NB." (PMID 37444427, 2023). "In the tumor microenvironment, however, this balance is tilted towards TIGIT, leading to tumor immune escape and immune depletion of effector cells, characterized by the upregulation of TIGIT and its multiple ligands." (PMID 37239949, 2023). "In myeloma mouse models, blocking of TIGIT was found to reduce tumour burden and prolong overall survival." (PMID 36297474, 2022). "This study explores the role of PD-1 and TIGIT signalling in OAC cells in either promoting or inhibiting the survival of OAC cells under characteristic features of the tumour microenvironment including nutrient-deprivation and hypoxia." (PMID 35245832, 2022). "In combination with PD-1/TIGIT blockade, neoantigen vaccination resulted in enhanced tumor regression." (PMID 36569934, 2022). "To explore mechanism of GIMAP4 underlying tumor-immune regulation, we calculated the correlations between GIMAP4 and 5 ICPs (CD274, CTLA4, TIGIT, LAG3, and PDCD1) and identified similar trends in their expression." (PMID 36246963, 2022). "Neoantigen vaccination was associated with a decrease in the percentage of regulatory T cells (Treg, CD4+CD25+FoxP3+) and, in particular, TIGIT+ Treg in the tumor, likely due to the increased absolute number of tumor-infiltrating CD4 T cells." (PMID 36569934, 2022). "The ability of CD8+TIGIT+ cells to secrete cytokines (TNF-α and IFN-γ) was significantly lower than that of CD8+TIGIT− cells, which indicated that CD8+TIGIT+ cells have low effector function and anti-tumor potential." (PMID 35729552, 2022).